IL6 (interleukin 6)
Diseases named in the same sentence as IL6 in open-access papers (continued):
Sharing a sentence is not in itself a finding about the gene and the disease.
diabetes (continued). "Similar activity and decreased levels of TNF-α, IL-1β, and IL-6 in serum were reported for fucoidan isolated from Saccharina japonica in a model of streptozotocin-induced diabetes mellitus in rats after 4 weeks of treatment." (PMID 37760952, 2023). "Results were similar when restricted to tuberculosis patients with diabetes and adjusting for HbA1c levels; cases experiencing recurrence or death had higher baseline IL-6 concentrations compared to controls (Table-2 and Figure-3)." (PMID 34711538, 2022). "Consistent with our previous results, the level of IL-6 and IL-10 in patients with diabetes was significantly elevated than those in HC individuals." (PMID 35242878, 2022). "The goal of this study was to evaluate the differential impact of growth, maternal diabetes, and chorioamnionitis on umbilical cord blood leptin and IL-6 levels." (PMID 35197933, 2022). "Other longitudinal studies have suggested elevated IL-6 and CRP levels associated with PD, as significant risk factors for insulin resistance and diabetes mellitus (DM)." (PMID 35629064, 2022). "In patients with diabetes mellitus, a reduced correlation was found between lactate and cytokine production, specifically for IL-6." (PMID 36337734, 2022). "In a murine diabetes model, proinflammatory cytokines, such as interleukin 6 (IL-6), monocyte chemoattractant protein-1 (MCP-1), and GM-CSF, were reduced in wounds, compared to wounds in non-diabetic mice." (PMID 36685591, 2022). "This review found evidence of the negative association between SB and fasting 2-h glucose, fasting insulin, 2-h insulin, incident diabetes and IL-6." (PMID 35544519, 2022). "Serum IL6 level can be a potential noninvasive marker of painful DPN, and it can help distinguish painful DPN from other causes of pain in patients with diabetes." (PMID 35155045, 2022). "Cytokine storm (IL-6), islet cell damage, elevated ferritin, and corticosteroid use in mainly patients with diabetes patients have led to a doubling of mucormycosis cases in India compared to 2019 and 2020." (PMID 35794908, 2022). "DPP4 inhibitors and IL-6 antagonists can be considered to reduce the effect of COVID-19 infection on patients with diabetes." (PMID 34996987, 2022). "In diabetes, renal cells (epithelial, mesangial, endothelial, and tubular cells) produce the cytokine of inflammatory IL-6 and TNF-α." (PMID 35685736, 2022). "On the other hand, IL-10/TNF-α, IL-10/IL-6, IL-10/IL-12, Gal-3/TNF-α, Gal-3/IL-6, and Gal-3/IL-12 (p = 0.001) were significantly higher (p < 0.05) in gonarthrosis with diabetes mellitus." (PMID 36141752, 2022). "In the mouse model, the levels of IL-6 and IL-10 were found to be significantly decreased in the latent tuberculosis with diabetes group in comparison to the latent tuberculosis only group." (PMID 36776550, 2022). "Anaemic patients with comorbidities (type 2 diabetes mellitus, hypertension, chronic obstructive pulmonary disease) had significantly higher IL-6 concentrations (x ̄=46.33 pg/mL) than anaemic patients without comorbidities (x ̄=21.92 pg/mL) (p = 0.005271)." (PMID 36612220, 2022). "Secondly, the size of the participants in this study is relatively small, and more cases are required to verify the variations of adiponectin, nesfatin-1, TNF-α, and IL-6 in prediabetes and diabetes, as well as to make the conclusion more convincing." (PMID 35311231, 2022). "Through inhibiting the IL-6 trans-signaling pathway in an early DR mouse model, diabetes-induced oxidative damage was significantly reduced at both systemic and retinal levels." (PMID 35624430, 2022). "Because it is primarily understood as an inflammatory marker, GlycA was related to CRP and partly also to IL-6 in the context of diabetes mellitus and in prediction models of cardiovascular incidents, where it proved to have considerable expressive power." (PMID 36557315, 2022).
diabetes (continued). "IL-6 pathway activation can induce hepcidin synthesis, and increments in IL-6 levels have been correlated with elevated glycemia in diabetes." (PMID 36431865, 2022). "Interleukin 6 (IL6) and tumor necrosis factor (TNF) are conventional pro-inflammatory cytokines believed to be risk factors for diabetes progression due to their disturbance of insulin signaling." (PMID 36432581, 2022). "The IL-6/JAK/STAT3 signalling pathway is implicated in various diseases including cancer and diabetes." (PMID 35562959, 2022). "It should be said that some inflammatory biomarkers such as TNF-α, interleukin 6 increase in diabetes." (PMID 36266683, 2022). "In particular, comorbid diabetes has been shown to propagate IL‐6 and INS gene expression, leading to increased ACE2 via NAD‐dependent histone deacetylase Sirtuin." (PMID 35644866, 2022). "BAT1 was identified as an anti-inflammatory gene through the modulation of pro-inflammatory cytokines tumor necrosis factor-alpha (TNF-α), interleukin-1 (IL-1), and interleukin-6 (IL-6) in diabetes, Chagas cardiomyopathy, and Plasmodium vivax malaria." (PMID 36505884, 2022). "For instance, in research relating to diabetes, KLF7 can directly bind to the promoter region in IL-6 and accelerate the overexpression of IL-6 in inflammatory signaling TLR4/NF-kB/IL-6, thereby causing inflammation." (PMID 35419025, 2022). "IL-6 is a clear contributor to the diabetes progression, as multiple clinical trials identified increased IL-6 mRNA expression T2D patients." (PMID 35597446, 2022). "As an example, the authors of a meta-analysis concluded, that chronic use of phosphodiesterase inhibitors in in type 2 diabetes mellitus patients has a beneficial effect on endothelial function conceivably by a reduction of IL-6 serum levels." (PMID 36209229, 2022). "In turn, these activate tumour necrosis factor-alpha (TNFα) and interleukin-6 (IL6), both of which exhibit increased serum levels with age and disease and mediate inflammation/fibrosis in multiple secondary complications of diabetes." (PMID 35054783, 2022). "Overexpression of miR-93-5p in the diabetic retina alleviates the microvascular degeneration, downregulates pro-inflammatory factors (IL-1β, IL-6, and TNF-α), and elevates antioxidant levels, including GSH and superoxide dismutase (SOD)." (PMID 36292956, 2022). "In training cohort, the independent risk factors for hospital mortality were increased age, diabetes, chronic renal diseases, decreased systolic blood pressure (SBP), and elevated fibrinogen, interleukin 6 (IL-6) and blood urea nitrogen (BUN)." (PMID 36117161, 2022). "ChREBP was also associated with up-regulation of several cytokines (TNF-α, IL-1β, and IL-6) in patients with type 2 diabetes mellitus, promoting the inflammatory responses and apoptosis of mesangial cells." (PMID 36741695, 2022). "The high-glucose environment of diabetes significantly increases the cytokines, such as interleukin 4(IL-4), interleukin 5(IL-5), interleukin 6(IL-6), interleukin 13(IL-13), and tumor necrosis factorα (TNF-α)." (PMID 35669482, 2022). "On the other hand, cytokines of inflammatory such as IL-6 and TNF-α also cause impaired function and damaged kidneys in diabetes." (PMID 35685736, 2022). "The underlying mechanisms linking periodontitis and diabetes have been considered to be pro-inflammatory cytokines derived from gingival lesions [tumor necrosis factor alpha (TNF-α), interleukin 6 (IL-6), and IL-17]." (PMID 36299624, 2022). "Early growth response 1 (Egr1) is another target gene of miR-150, and knockdown of this target alleviates the diabetes-induced inflammation in mouse mesangial cells by downregulating pro-inflammatory factors (IL-1β, IL-6, and TNF-α)." (PMID 36292956, 2022). "Regarding biochemical parameters, in addition to glucose, which was expected to be higher in subjects with diabetes, the “Diabetic” group also presented higher values of triglycerides, systolic blood pressure, IL-6, and TNF-α." (PMID 35336365, 2022).
diabetes (continued). "In line with this, the proinflammatory cytokines, IL1B and IL6 were downregulated on the mRNA level in urine exfoliated cells from patients with diabetes." (PMID 36127330, 2022). "No statistical differences were found in the age, genders, duration of diabetes, concomitant risk factors, BMI, FPG, 2h-PBG, HbA1c, TC, TG, SCr, BUN, TNF-α, IL-6, and hs-CRP between both the groups (P > 0.05)." (PMID 36177313, 2022). "Next, we found that ZAF, BRO and the combination of ZAF and BRO reduced the transcription and expression level of proinflammatory cytokine IL-1β and IL-6 of the hippocampus of diabetes mice, respectively." (PMID 36378718, 2022). "The induction of diabetes increased the levels of IL-1β, IL-6, and TNF-α in the DCM model, and these effects were inhibited by PQQ." (PMID 34997266, 2022). "Multiple studies have identified links between diabetes and inflammatory markers, such as tumor necrosis factor-α, interleukin-6, and C-reactive protein." (PMID 35971094, 2022). "In a multivariate analysis, higher total subcutaneous adipose tissue fibrosis adjusted for age, diabetes and circulating IL-6 characterized the LR group (OR [95% CI] = 1.58 [1.10-2.28])." (PMID 35574032, 2022). "For example, telomerase directly regulates NF-κB-dependent gene expression, such as that of IL6 and TNFα; cytokines were previously shown to be involved in the inflammatory pathogenetic pathways of the complications of diabetes and cancer." (PMID 35628895, 2022). "They found out that IL-6 exerts proinflammatory effects in the pathophysiology of both diabetes and CKD." (PMID 36363561, 2022). "More importantly, the mechanisms of how adiponectin, nesfatin-1, TNF-α, and IL-6 are involved in the progression of prediabetes toward diabetes are worth our in-depth exploration." (PMID 35311231, 2022). "SASP marker, IL-6, was increased in renal cortex of mice with diabetes and its gene expression was significantly decreased by the genetic deletion of C5aR1, in C5aR1 knockout (KO) mice." (PMID 36434087, 2022). "In parallel with this line of evidence, apigenin was reported to decrease renal IL-6 expression in diabetes or doxorubicin-induced nephropathy." (PMID 36422572, 2022). "For example, C-reactive protein and interleukin-6, typical inflammatory factors, were present at a high level in patients with diabetes and frailty." (PMID 36726468, 2022). "IL-6 has been shown to be correleted with the development of complications in diabetes, including diabetic neuropathy, in which high levels of IL-6 are associated with increased nerve degeneration." (PMID 36248900, 2022). "Interleukin-6 (IL-6), an inflammatory mediator produced by diabetes, activates the JAK-signal transducer and activator of transcription 3 (STAT3) signaling pathway." (PMID 36497173, 2022). "We compared leptin and IL-6 level across two common perinatal conditions that are coupled with inflammation, diabetes and chorioamnionitis." (PMID 35197933, 2022). "Conclusive detrimental associations with sedentary behaviour were determined for 2-h insulin (6/12 studies found associations), fasting insulin (15/19 studies), insulin sensitivity (4/6 studies), diabetes (3/4 studies) and IL-6 (2/3 studies)." (PMID 35544519, 2022). "Diabetes aggravated adverse cardiac remodeling, increased the mortality rate, cardiac hypertrophy, the fibrotic area, and enhanced IL-1β, IL-6, TNF-α, and IL-18 expression in myocardial tissue." (PMID 36320147, 2022). "The pro-inflammatory markers TNF-α, IL-6 and insulin-like growth factor (IGF), associated with visceral adiposity and diabetes, are associated in vivo and in vitro models with HCC development and progression." (PMID 36145251, 2022). "SARS-CoV-2 infection leads to increased levels of inflammatory cytokines such as TNF-α, IL-1, and IL-6, which are also increased in diabetes." (PMID 36079032, 2022). "A number of markers of inflammation are elevated in patients with diabetes, including the leukocyte count, IL-6, TNF-α, and CRP." (PMID 36615781, 2022).
diabetes (continued). "Hyperglycemia was significantly associated with a new onset of frailty in the adjusted model controlling for BMI, IL-6, and chronic morbidities such as diabetes mellitus, osteoarthritis, COPD, CAD, and peripheral renal disease." (PMID 35795135, 2022). "Several findings have shown incidence of diabetes following high levels of IL6 among other markers such as CRP." (PMID 36561566, 2022). "In diabetes, there would be an increase in pro-atherogenic monocyte activity such as IL-6 and IL-1β production." (PMID 34330221, 2021). "IL-6 is often considered as a pro-inflammatory cytokine, stimulating inflammatory and auto-immune processes related to multiple diseases such as diabetes, atherosclerosis, Alzheimer’s disease and cancer." (PMID 33466835, 2021). "Consistent odds were observed for stroke while controlling for different combinations of uncontrolled diabetes, TNFα and IL6." (PMID 33510184, 2021). "Recently it has been reported that Ninj1 is significantly upregulated in diabetes patients, and that functional blocking of Ninj1 attenuates IL-6 and MCP-1 overexpression and protects vascular defects." (PMID 33924583, 2021). "For example, diabetes, a prevalent comorbidity in our study, is characterized by an exaggerated pro-inflammatory cytokine response, notably interleukin-1 (IL), IL-6, and tumor necrosis factor (TNF)-α." (PMID 34872493, 2021). "IL-6 stimulates the inflammatory and auto-immune process in many diseases such as diabetes, cancer and Alzheimer’s disease." (PMID 33675295, 2021). "Increased expression of IL-1β in the glomeruli of STZ-induced diabetes and significant increase of IL-6 in diabetic subjects especially in the mesangium, interstitium, and the tubules have been documented." (PMID 33562428, 2021). "Our results revealed that TNF-α and IL-6, and NF-κB were elevated in the T2D myocardium, which confirms the involvement of inflammation in the pathogenesis of diabetes-induced cardiac injury." (PMID 34497520, 2021). "Inflammation markers such as c-reactive protein (CRP) and IL-6 are involved in insulin resistance, which positively correlates with the progress of diabetes." (PMID 34539410, 2021). "Non-survivors of diabetic cases showed the significant increases of IL-6 and IL-8 at week 2 compared to that at week 1, whereas there were greatly reductions in survivors of diabetes cases." (PMID 33776910, 2021). "High blood pressure increases inflammatory markers, such as C-reactive protein, interleukin 6 and adhesion molecules related to the insulin signaling pathway and β-cell function, and further leads to the incident diabetes." (PMID 33926442, 2021). "NF-κB, a transcription factor that controls numerous pro-inflammatory proteins production (including TNF-α, IL-6 and IL- 1β), has been recognized to be crucial in the development of diabetes and obesity-related diseases." (PMID 34571976, 2021). "Leptin and interleukin-6 (IL-6) have proatherogenic effects, contributing to the development of classic risk factors for atherosclerosis including, arterial hypertension, diabetes mellitus (DM), endothelial dysfunction, inflammation and platelet activation." (PMID 33735200, 2021). "The levels of GFAP and the secretion of TNF-α, IL-1β, and IL-6 were significantly increased in the retinas of mice with diabetes compared with those of the mice in the normal group." (PMID 34938383, 2021). "In this current study, we determined that administering one weekly 100 μL subcutaneous injection of saline containing 20 μM of XMD8-92 was sufficient to ameliorate diabetes-mediated IL-6 and VEGF production, and significantly decreased IL-1β in diabetic mice." (PMID 34456740, 2021). "Diabetes is associated with an increase in plasma TNF, IL-1β, interleukin 6 (IL-6), interferon-g (IFNγ), and PAI-1, as well as alteration in immune cell response leading to chronic low-grade inflammation." (PMID 34054705, 2021).
diabetes (continued). "The neutralization of IL-6 in diabetic mice completely reversed the renal fibrotic phenotype, suggesting a critical pro-fibrotic role of IL-6 in diabetes." (PMID 33888696, 2021). "Indeed, diabetes can cause a chronic activation of the immune system with increased levels of circulating leukocytes and pro-inflammatory markers; these include serum levels of inflammation-related biomarkers such as IL-6, C-reactive protein, serum ferritin and the D-dimer coagulation index." (PMID 33975613, 2021). "Our results in mice are consistent with the study of a streptozotocin-induced diabetes rat model, wherein increased levels of the proinflammatory cytokines IL-6, TNF-α, and IL-1β were found in diabetic rat pancreatic tissue." (PMID 33774704, 2021). "Increased the ratio of RANKL/OPG and the secretion of AGEs, reactive oxygen species (ROS), TNF-α, IL-1β, and IL-6 in diabetes enhance periodontal ligament (PDL) and osteoblast apoptosis, induces osteoclastogenesis, and reduces bone formation." (PMID 34539410, 2021). "We chose to use 1 ng/ml IL-1β empirically, because this concentration promoted elevated expression of TNFα, IL-1β, IL-6 and IL-8 in hMC cultures like that observed in the vitreous of diabetic patients and retina of experimental diabetes models." (PMID 33958662, 2021). "We found that treatment with either MSI-1436 or AAV2-Cryba1 construct for 2 months following diabetes onset did reduce IL-6 and IL-1α levels as well as capillary degeneration." (PMID 33627831, 2021). "Under “diabetes-like” conditions, WT HspB4/αA-crystallin overexpression led to the significant reduction of the induction of IL-6 (55%), IL-1β (36%), IL-18 (93%), and MCP-1 (85%) by MGCs (HspB4−/−)." (PMID 34071438, 2021). "Thus, IL-6 may be a potential target to treat nephropathy caused by diabetes in clinic." (PMID 34054555, 2021). "We found that diabetes significantly increases pro‐inflammatory factor levels (IL‐6 and IL‐1β), and FGF1 treatment remarkably reversed them." (PMID 33788387, 2021). "Their study revealed that whole blood cells from diabetes participants were less capable of producing IL-6 after LPS stimulation, when compared with healthy controls." (PMID 34681832, 2021). "Increased levels of cyclooxygenase-2 (cox-2), interleukin–6 (IL-6), and tumour necrosis factor-alpha (TNF-α) are associated with the inflammatory response and in diabetes, and increased levels of these contribute to chronic wounds that do not heal." (PMID 33628374, 2021). "Chronic inflammation in diabetes is characterized by increased inflammatory cytokines such as interleukin 6 (IL-6), and interleukin (IL-1)." (PMID 34125859, 2021). "Studies have reported that diabetes-induced gliosis eventually leads to the production and release by MGCs of inflammatory molecules such as interleukin-1β (IL-1β), interleukin-6 (IL-6), tumor necrosis factor-α (TNF-α), and chemokine ligand-2 (CCL2)." (PMID 34071438, 2021). "Actually, IL‐6 acts via two distinct signalling pathways in the development of diabetes, that is, classic signalling and trans‐signalling." (PMID 33960655, 2021). "Like AA, LXA4 prevented the development of alloxan- and streptozotocin-induced type 1 and type 2 diabetes mellitus, respectively, and suppressed IL-6 and TNF-α production and NF-kB expression." (PMID 34944517, 2021). "As for the Th2 cytokines, the IL-6 and IL-10 levels in patients with diabetes in week 1–3, and IL-8 in week 1–3 were significantly higher than those in patients without diabetes." (PMID 33776910, 2021). "Meta-analytic results indicate that IL-6 is the most sensitive inflammatory marker that predicts subsequent diabetes in initially healthy samples, and concentrations of IL-6 are elevated in patients with type 2 diabetes." (PMID 34206644, 2021). "According to the available studies, fibrinogen, interleukin-6 (IL-6), and tumor necrosis factor-α (TNF-α) are associated with the onset of diabetes." (PMID 34712322, 2021).